RASSF4 (Ras association domain family member 4)
Diseases named in the same sentence as RASSF4 in open-access papers (continued):
Sharing a sentence is not in itself a finding about the gene and the disease.
cancer (9 papers, 2015 to 2025). A tumor composed of atypical neoplastic, often pleomorphic cells that invade other tissues. "HDACs regulate the expression of many cancer-associated proteins including p21WAF1 and RASSF4 through histone modification." (PMID 30987296, 2019). "a highly aggressive childhood muscle-derived cancer in which the oncogenic fusion protein paired box 3–forkhead box O1 (PAX3-FOXO1) stimulates the RASSF4 protein expression." (PMID 41007433, 2025). "On the other hand, for specific pathological states driven by RASSF4 overexpression, such as certain cancer subtypes, RNA interference technology or CRISPR-Cas9 gene editing systems are required to specifically inhibit RASSF4 expression." (PMID 41007433, 2025). "This review explains how RASSF4 is controlled by chemical changes that switch it on or off, and how its behavior changes across cancer types." (PMID 41007433, 2025). "We discuss poten-tial treatments aimed at restoring RASSF4’s protective function in cancers where it is silenced, or blocking its harmful effects where it is overactive." (PMID 41007433, 2025). "Member 4 of the RAS-related domain family (RASSF4), which is abnormally expressed in human cancers, participates in carcinogenesis and has an inhibitory effect on biological processes." (PMID 35832790, 2022). "RASSF4 effectively inhibits the proliferation and invasion of cancer cells, acting as an important tumor suppressor." (PMID 35832790, 2022). "In various malignant tumors, the CpG islands enriched in the 5′ promoter region of the RASSF4 gene often undergo abnormal methylation modifications, a process primarily mediated by DNA methyltransferases 1 (DNMT1) and DNMT3A/B, leading to transcriptional silencing of the gene." (PMID 41007433, 2025). "RASSF4 is a gene that plays two different roles in cancer depending on the context." (PMID 41007433, 2025). "Restoring the RASSF4 function may emerge as a new therapeutic approach for interfering with cancer stem cells." (PMID 41007433, 2025). "Previous studies indicated RASSF4 downregulation in several human cancers." (PMID 35611809, 2022). "In addition, we also found that the presence of HDAC7 led to the upregulation of genes related to immune processes (IL16, FCGR2A, IRAK2, CD86 and CD40, among others) and cancer (RASSF4, RAB31, NEDD9 and RASSF2, among others)." (PMID 25675295, 2015). "In contrast, RASSF4 is more challenging to study because of its environmental dependence on its expression and function—its cancer-suppressive function needs to be restored in most cancer types, while in some specific tumors, its pro-cancer activity needs to be suppressed." (PMID 41007433, 2025). "There have been comparatively few studies of RASSF3, RASSF4, and RASSF8, though it is clear their expression is downregulated in numerous human cancers." (PMID 39009833, 2024). "This dependency may be related to differences in specific transcription factors regulating RASSF4 (such as ZF5, Pax-5, and AHR) across different cancers and their interactions with DNMT, which promote site-specific methylation." (PMID 41007433, 2025). "Our results were further supported by TCGA data analysis, showing RASSF4 downregulation in CRC cancers and its negative correlation with pathological stage." (PMID 35611809, 2022).
infection (1 paper, 2014). The state of being infected such as from the introduction of a foreign agent such as serum, vaccine, antigenic substance or organism. "For example, CD28, a protein known to decrease apoptosis of T lymphocytes and to increase migration of memory T cells was down-regulated after YFV-DakH1279 infection whereas, RASSF4, a gene believed to be involved in apoptosis, was up-regulated." (PMID 25412185, 2014).
metabolic disease (1 paper, 2025). A congenital disorder (due to inherited enzyme abnormality) or acquired (due to failure of a metabolically important organ) disorder resulting from an abnormal metabolic process. "In contrast, gene intervention strategies that directly target RASSF4 achieve precise gene delivery and stable expression through viral and non-viral vector systems, providing more direct and effective treatment options for patients with advanced tumors and metabolic diseases." (PMID 41007433, 2025).
RASSF4 also shares sentences with these, for which no sentence is quoted: epithelioid hemangioendothelioma (1 paper); mesenchymal tumors (1); pheochromocytoma (1); prostate carcinoma (1); sarcoma (1); thyroid tumor (1).